RNASEH1-DT (RNASEH1 divergent transcript)
Synonyms: LOC100506054; RNASEH1-AS1
Gene: Long non-coding RNA gene on chromosome 2 (3,558,375 to 3,564,842, forward strand). Ensembl gene ENSG00000234171.
Diseases named in the same sentence as RNASEH1-DT in open-access papers:
RNASEH1-DT is named in the same sentence as 1 disease in open-access papers, as found by Europe PMC text mining. Sharing a sentence is not in itself a finding about the gene and the disease.
RNASEH1-DT shares sentences with these, for which no sentence is quoted: non-small cell lung carcinoma (1 paper).